RNU6-1069P (RNA, U6 small nuclear 1069, pseudogene)
Gene: Small nuclear RNA gene on chromosome 12 (31,802,958 to 31,803,090, reverse strand). Ensembl gene ENSG00000252421.
Homologues: Orthologues: chimpanzee U6 (98% identical), macaque U6 (71% identical), guinea pig U6 (58% identical), pig U6 (55% identical). Paralogues in human: RNU6-1060P (62% identical), RNU6-140P (62% identical), RNU6-49P (62% identical), RNU6-1011P (61% identical), RNU6-1124P (61% identical), RNU6-1152P (61% identical), RNU6-19P (61% identical), RNU6-338P (61% identical), RNU6-48P (61% identical), RNU6-641P (61% identical), RNU6-657P (61% identical), RNU6-820P (61% identical), and 1282 more.